IL6 (interleukin 6)
Diseases named in the same sentence as IL6 in open-access papers (continued):
Sharing a sentence is not in itself a finding about the gene and the disease.
pulmonary fibrosis (continued). "In our study, both ESR and fibrinogen demonstrated a significant association with lung fibrosis at the 3-month and 2-year evaluations, with ESR showing higher correlation coefficients and AUC values compared to other inflammatory markers such as CRP, fibrinogen, ferritin, IL-1 and IL-6." (PMID 39767173, 2024). "CA-induced increased concentrations of inflammatory factors such as IL-1, IL-6, and IL-8 may also aggravate the pulmonary inflammation via increasing pulmonary vascular resistance, hindering alveolar development, accelerating pulmonary fibrosis, and ultimately leading to BPD." (PMID 37654686, 2023). "Recent studies showed that HFD could significantly increase the histone H3 trimethylation at lysine 4 (H3K4Me3) while increased H3K4Me3 level at the interleukin 6 (Il-6) promoter region could promote its expression which subsequently contributed to lung fibrosis through enhancing EMT." (PMID 36979493, 2023). "Hence, a combination therapy targeting the anti-inflammatory (such as IL-6 blockades) and anti-fibrotic pathways (such as Pirfenidone) may be a potential therapeutical strategy for long COVID with pulmonary fibrosis." (PMID 36744129, 2023). "Indirect evidence: transforming growth factor TGF-β, tumor necrosis factor TNF-α, and interleukin IL-6 were elevated in lung tissues, and the therapeutic value of two drugs (Pirfenidone and Nintedanib) for idiopathic pulmonary fibrosis in COVID-19-induced pulmonary fibrosis." (PMID 38144556, 2023). "Moreover, IL6 mRNA expression was significantly increased in Plaur-/- mice 14 days after bleomycin instillation (p < 0.05, 2-way ANOVA, Holm–Šídák’s test), confirming uPA and IL-6 in lung fibrosis to be intertwined and closely linked." (PMID 36674896, 2023). "Moreover, monotherapy by L. minor protect the connective tissue deposition in the lungs which is evident from the statistically insignificantly decreased or commensurate to the control levels of the lung fibrosis-related IL-1β, IL-6, and TNF-α concentration, respectively." (PMID 35326173, 2022). "Besides, it is growing recognized that cytokine IL-6 plays a crucial role in pulmonary fibrosis." (PMID 36544757, 2022). "In the BLM-induced model of pulmonary fibrosis, myeloid PTEN-deficient mice exhibited enhanced TGF-β1 activation and collagen deposition, decreased number of macrophages and T cells, and aberrant macrophage polarization with augmentation of various proinflammatory cytokines such as IL-6 and TNF-α." (PMID 35814272, 2022). "The same study revealed that intraperitoneal administration of hAECs could downregulate proinflammatory cytokines such as TNF-α, TGF-β, IFN-γ, and IL-6 and also diminish subsequent pulmonary fibrosis by lowering pulmonary collagen deposition, levels of α-SMA, and inflammatory cells infiltration." (PMID 35337387, 2022). "Interestingly, IL-6 plays a biphasic role in the pathogenesis of pulmonary fibrosis." (PMID 34530920, 2021). "Furthermore, blockade of IL6 signalling in an in vivo mouse model abrogates pulmonary fibrosis." (PMID 34028807, 2021). "Similarly, adoptive transfer of topo I-APC+ topo I-PE+ CD19+ cells obtained from IL-6 or IL-23-deficient mice immunized with topo I four times into non-immunized wild-type mice did not induce skin and lung fibrosis." (PMID 34854378, 2021). "Indeed, reduction in IL6 alone is therapeutic in pulmonary fibrosis." (PMID 34660588, 2021). "Moreover, inflammatory cytokines such as IL6, which play an important role in the development of lung fibrosis, might also act as potential therapeutic targets for its treatment." (PMID 34681944, 2021). "Since the SF-MSC treatment inhibited the increased IL-6 and decreased TGF-both of which are associated with Treg induction, we hypothesized that SF-MSC treatment could induce differentiation of Tregs in BLM-treated mice and prevent lung fibrosis." (PMID 34530920, 2021).
pulmonary fibrosis (continued). "Since the proportion of connective tissue mast cells in small airways correlated negatively with lung function, mast cell-derived IL-6 could be a target for inhibition in CF patients, especially considering successful use of IL-6 trans-signaling blockade in a mouse model of pulmonary fibrosis." (PMID 32397175, 2020). "Our data also supported that IL-6 may be an important marker and target cytokine for preventing body weight loss and skeletal muscle atrophy in the clinical care of several chronic lung diseases, including COPD and pulmonary fibrosis." (PMID 31049028, 2019). "Therefore, the aim of this study was to determine the impact of IL-6 in PQ-induced pulmonary fibrosis and to explore whether the epigenetic regulators play a role in the transcriptional regulation of IL-6." (PMID 28194150, 2016). "Therefore, histone acetylation potently regulates the expression of IL-6 gene in macrophages which may be of significance in the treatment of diseases that result from the overproduction of IL-6, such as PQ-induced pulmonary fibrosis." (PMID 28194150, 2016). "Mangiferin (MANG) and gentiopicroside (GENPD) have been shown to have an anti-fibrotic effect in preclinical studies for treating pulmonary fibrosis by regulating inflammatory markers (TNF, IL-17, and IL-6) and TGFβ1/Smad and TNF-α/NF-κB signalings." (PMID 41361355, 2025). "Previous studies in idiopathic pulmonary fibrosis (IPF), have shown increased levels of IL-6 in patients with acute exacerbation of IPF, compared with patients with stable IPF." (PMID 40739515, 2025). "Aminaphtone appears to reduce the transcription and protein production of key inflammatory mediators, including IL-6, and it also lowers TGF-β levels, which can contribute to pulmonary fibrosis by stimulating fibroblasts to excessively deposit collagen." (PMID 40006015, 2025). "Nonetheless, in both species, we confirmed a P2RX4/IL-6/ARG1, myeloid-mesenchymal circuit that is functionally important in lung fibrosis." (PMID 40875483, 2025). "In mice treated with BLM, atRA attenuated the upregulation of IL-17A, IL-10, IL-6, EphA2, EphriA1, PI3K 110γ, Akt, IL-6, TNF-α, and TGFβ1, which reduced pulmonary fibrosis and significantly alleviated lung fibrosis." (PMID 40508111, 2025). "Inflammatory cytokines, including TNF-α, IL-1β, IL-6, and TGF-β1, are recognized to play a role in the initiation and progression of pulmonary fibrosis." (PMID 40665395, 2025). "Similar to IL-6, TNF-α contributes to lung fibrosis by promoting inflammation, oxidative stress, tissue remodeling, and fibroblast activation, and its levels are elevated in IPF patients and experimental models." (PMID 40630478, 2025). "Critically, our study extends this paradigm to pulmonary fibrosis: FSTL1 overexpression in A549 cells amplified NF-κB and cytokines (IL-1β/TNF-α/IL-6), FSTL1 inhibition attenuated TGF-β1-induced inflammation." (PMID 40808692, 2025). "We found that the expression levels of p-NF-κB, IL1, IL6, and TNF-α were significantly upregulated in the pulmonary fibrosis model mice, while their expression was significantly inhibited after treatment with SGZ." (PMID 40731787, 2025). "In vitro experiments indicated that SM injection alleviated pulmonary fibrosis by downregulating MMP9, IL-6, and TNF-α." (PMID 40630478, 2025). "Using the bleomycin (blm) mouse model of pulmonary fibrosis, we demonstrate that AHR+ DCs accumulate in the lungs and drive production of IL-6 in an AHR-dependent fashion." (PMID 39964756, 2025). "A previous study reported that the fenugreek seed extract reduced IL-6 in an ovariectomized rat model and downregulated NF-κB, TNF-α, IL-6, IL-8, and IL-1β in a pulmonary fibrosis animal model." (PMID 39941027, 2025). "This suggests that the MMP9, IL-6, and TNF-α collectively exert multiple effects in driving lung fibrosis progression." (PMID 40630478, 2025).
pulmonary fibrosis (continued). "MiRNA-21a-5p overexpression promoted lung fibrosis in bleomycin-induced SSc mice, inducing infiltration of cells expressing TNF-α, IL-1β, IL-6, or IL-17, along with STAT3 phosphorylated cells in the lesional skin." (PMID 38561750, 2024). "The inflammatory markers IL-6, IL-8 and MCP-1 are recognised as drivers in pulmonary fibrosis but also in COPD pathology." (PMID 39014439, 2024). "For example, ARDS can induce pulmonary fibrosis through excessive TH17 immunity, triggered by IL-17, IL-6, and TGF-β." (PMID 39170360, 2024). "In the lung tissues, IL-6, osteopontin, IFNγ, and MCP-1 levels were markedly increased in WT and TG mice with lung fibrosis compared to their respective saline-treated controls." (PMID 39329706, 2024). "In pulmonary fibrosis models, following stimulation by TGF-β1, Brd4 occupies the promoters of interleukin-6 (IL-6), α-smooth muscle actin (α-SMA), and plasminogen activator inhibitor-1 (PAI-1), thereby promoting fibrosis." (PMID 39026235, 2024). "These lipid-lowering agents attenuated airway hyperresponsiveness, macrophages in BALF, lung fibrosis, serum leptin, free fatty acids, TGF-β1, IL-1β, IL-6, and IL-17a in the lung." (PMID 38762465, 2024). "The pathogenesis of pulmonary fibrosis involves various mediators such as TGF-β, legumain, osteopontin, IL-4, IL-6, IL-13, IL-17, TNF-α, Gal-1, Gal-3, PDGF, and FGFR-1." (PMID 38540252, 2024). "iPSCs also, can downregulate the pro-fibrotic growth factors IGF-1,2, and repress several inflammatory mediators during pulmonary fibrosis, including TNF-α, IL-1β, IL-6, inducible nitric oxide synthase (iNOS) and nitric oxide (NO), but also PGE2." (PMID 38886859, 2024). "In vivo, increased WNT/β-catenin signaling leads to the expression of the pro-inflammatory cytokines IL-1β and IL-6 in alveolar epithelial type cells in the bleomycin model, and it provides a WNT/interleukin axis link in the development of pulmonary fibrosis." (PMID 39596365, 2024). "Several studies have confirmed elevated BMP2 receptor levels induced by IL-6 signaling can activate SMAD1/5/8 and dampen the SMAD 2/3 pathway in idiopathic pulmonary fibrosis." (PMID 39334820, 2024). "As reported, inhibition of certain signaling pathways can ameliorate bleomycin-induced pulmonary fibrosis, such as NF-κB/NLRP3 signaling-mediated inflammation, the IL-1β/IL-1R1/MyD88/NF-κB axis, and IL-6/STAT3 pathway." (PMID 38913698, 2024). "Overproduction of inflammatory mediators and cytokines, such as inflammasome complexes, IL‐6, IL‐1β, and TNF‐α, can also lead to lung fibrosis in affected patients." (PMID 37773712, 2023). "In our 14-day BLM model of lung fibrosis, RP-832c also significantly decreased the mRNA expression levels of multiple cytokines, including TNF-α, IL-6, IL-10, and IFN-γ in the lung." (PMID 37174654, 2023). "In turn, IL-6 is known to upregulate ACE2, a.k.a “SARS-CoV-2 receptor”; thus, we also analyzed ACE2 expression in mice lungs after bleomycin-induced pulmonary fibrosis." (PMID 36674896, 2023). "The inflammatory markers IL-6, IL-8 and MCP-1 are recognised as drivers in pulmonary fibrosis but also in COPD." (PMID 36994416, 2023). "Increasing evidence has shown that IL-1β, IL-6, and TNF-α contribute to the pathogenesis of pulmonary fibrosis." (PMID 36830999, 2023). "A relationship was also observed between the markers of progression to pulmonary fibrosis (i.e., YKL-40 and KL-6), IL-6, IL-10, and IL-13 cytokines and mortality." (PMID 36975498, 2023). "Overproduction of inflammatory mediators and cytokines such as inflammasome complexes, IL‐6, IL‐1β, TNF‐α, and the like leads to lung fibrosis in affected patients." (PMID 37773712, 2023). "GSEA showed that DEGs in the CIP associated myeloid cell subclusters were enriched in inflammation pathway such as IFN, IL2, IL6, TNF signaling, and lung fibrosis." (PMID 37653115, 2023).
pulmonary fibrosis (continued). "Conversely, depletion of TRIM33 leads to increased production of TGF-β1, inducing idiopathic pulmonary fibrosis (IPF) and interstitial lung inflammation through Smad4 and downstream inflammatory factors such as TNF-α and IL-6." (PMID 37415133, 2023). "Both uPAR and IL-6 regulate EMT progression, a process that actively contributes to pulmonary fibrosis upon lung injury." (PMID 36674896, 2023). "From a RA-ILD mice model developed by CIA with BLM-induced pulmonary fibrosis, expressions of TNF-α and IL-6 in the ankle joints of mice were upregulated compared to the control group." (PMID 37833957, 2023). "Their vivo study demonstrated that pre-treatment with GW4869 decreased lung fibrosis and the expression of TNF-α, IL-1β, and IL-6 in silicosis model." (PMID 35677105, 2022). "STAT3 regulates IL-6- and TGF-β-mediated myofibroblast differentiation and the epithelial-to-mesenchymal transition (EMT) in pulmonary fibrosis." (PMID 36556326, 2022). "In our research, the SASP IL-6 and TGF-β levels in the o-PF group were higher than in the other three groups, suggesting that high levels of pro-fibrotic cytokines aggravate pulmonary fibrosis in old rats." (PMID 36556326, 2022). "The inflammatory activities of IL-1β, IL-6, MPO, TGF-β1, and TNF-α in the lung tissues of both normal control rats and BLM-induced lung fibrosis rat models were determined." (PMID 35268069, 2022). "In previous studies, laboratory findings (including interleukin-6 (IL-6), LDH, interferon-gamma, and KL-6 levels) have been suggested to be prognostic factors for pulmonary fibrosis." (PMID 36233779, 2022). "In this study, hMIKO-1 administration suppressed pulmonary fibrosis and the expression of F4/80, inflammatory cytokines (TNF-α, IL-6, and IL-1β), and fibrotic factors in the lungs of BLM-ILD mice." (PMID 36077067, 2022). "Interluekin‐6 (IL6), a key pro‐inflammatory cytokine, is released from ATII cells and its expression is increased in the hyperplastic alveolar epithelium in pulmonary fibrosis." (PMID 34028807, 2021). "This is in keeping with our previous work and also recent work in lung fibrosis and most recently bone marrow-derived stromal cells were found to upregulate Gremlin-1 via IL-6 trans signaling and this could be retarded with the use of an IL-6 monoclonal antibody." (PMID 34150776, 2021). "Luteolin also reduced the production of IL-6, TGF-β, ROS, and histological signs of pulmonary fibrosis including such as α-SMA and TGF-β1." (PMID 34221077, 2021). "Increased levels of IL1ꞵ, IL2, IL6, IL8, IL10, and IL12 have been reported in the bronchoalveolar lavage fluid and/or serum of patients with pulmonary fibrosis compared to healthy subjects." (PMID 34960806, 2021). "According to the existing studies, the development of pulmonary fibrosis in the patients with SARS-CoV-2 infection is accompanied by the increased expression of cytokines such as TGF-β, TNF-α, IL-1β, IL-6 and IL-13." (PMID 34876129, 2021). "In the current study, we observed the upregulation of retinol-metabolizing pathway molecules, recovery of the expression of RALDH, and suppressed expression of IL-6 and TGF-β in BLM-induced pulmonary fibrosis treated with CD45−/ALDHbr cell therapy." (PMID 34425896, 2021). "The cell count and cytokines (IL-1β, IL-6, and IL-8) of bronchoalveolar lavage (BAL) fluid were also increased in bleomycin-induced lung fibrosis in rat." (PMID 34742261, 2021). "Bleomycin-induced pulmonary fibrosis and respiratory inflammation in mice mimic ALI, in which IL6 is abnormally upregulated." (PMID 35126382, 2021). "WT mice, IL-6-deficient (IL-6KO), and IL-23-deficient (IL-23KO) mice were immunized four times with topo I. Then, 104 cells of topo I-reactive B cells obtained were transferred to non-immunized WT mice, and the dermal thickness and lung fibrosis score were measured 14 days later." (PMID 34854378, 2021).
pulmonary fibrosis (continued). "The effects include reduced in the levels of inflammatory mediators such as IL-6 and TNF-α, improved pulmonary angiogenesis, ameliorated lung fibrosis and restored alveolar structures in BPD experimental models." (PMID 33791258, 2021). "Liposomal quercetin was demonstrated to attenuate bleomycin-induced pulmonary fibrosis in vivo by the suppression of inflammatory cytokines (TNF-α, IL-1β, and IL-6) and the diminish of total cells and macrophage counts in BALF." (PMID 35126133, 2021). "More importantly, an in vivo study demonstrated that pre‐treatment with GW4869 decreased lung fibrosis and the expression of TNF‐α, IL‐1β and IL‐6 in BALF." (PMID 33834616, 2021). "In addition, Hsp90 could also contribute to the development of lung fibrosis through IL-6." (PMID 33414495, 2021). "Seen from this viewpoint, SF-MSC treatment in the current study suppressed the serum and BALF levels of IL-6, especially in the late phase, suggesting that SF-MSC administration reasonably ameliorates established pulmonary fibrosis." (PMID 34530920, 2021). "In fibrotic diseases, several of IL-6 family cytokines including IL6 and OSM have been shown to induce pulmonary fibrosis, but the contribution of IL-31/IL-31RA signaling in lung fibrosis has remained unexplored." (PMID 33815402, 2021). "Studies have observed that statins attenuate the inflammatory effect of IL-6 and IL-17 and modulate the anti-inflammatory effect of ACE2 in both ILD-PF and infection-induced pulmonary fibrosis, leading to reduced risks of CAD and stroke." (PMID 34705851, 2021). "Our analysis showed that eight genes (CSF2, CSF3, CXCL2, CXCL8, IL1B, IL6, MMP9, and TNF) are significantly overlapping with the lung fibrosis pathway with p-value 9.35e-11." (PMID 33362771, 2020). "A former study proved that Feibi Recipe can effectively inhibit the overexpression of IL-6/TGFβ1/P38MAPK cell signaling pathway and reduce pulmonary fibrosis of the bleomycin model rat." (PMID 33101446, 2020). "In summary, we demonstrated that immune-checkpoint CD47, PD-L1 and IL-6 signaling was markedly upregulated in a JUN-dependent fashion in pulmonary fibrosis patients and mouse lung-fibrosis models." (PMID 32493933, 2020). "Among eight serum cytokines, chemokines, and growth factors (IL-6, IL-8, IL-10, CCL2, CXCL10, CX3CL1, FGF-2, and VEGF), only IL-6 was found to be an independent predictor of the DLco decline in both SSc-ILD and idiopathic pulmonary fibrosis." (PMID 33105647, 2020). "In our investigation, when compared with the control group, the levels of MDA, TNF-α, and IL-6 were dramatically increased and SOD was dramatically reduced in Blm-treated pulmonary fibrosis mice lung tissues." (PMID 33192501, 2020). "In the absence of FOXM1, the p38 MAPK pathway is activated in macrophages leading to production of pro-fibrotic mediators IL-1β, IL-6 and TNF-α that directly stimulate fibroblast activation and survival, exacerbating pulmonary fibrosis." (PMID 32271749, 2020). "The secretion of cytokines, including IL-1β, IL-6, TNF-α, and MCP-1, plays a certain role in the pathogenesis of pulmonary fibrosis." (PMID 31947943, 2020). "Whereas IL-6-neutralizing antibodies ameliorate lung fibrosis at early fibrotic stages of BLM-induced lung injury, blockade of the IL-6 pathway accelerates the development of lung fibrosis at the early inflammatory stage in the BLM-induced PF mice model." (PMID 32587955, 2020). "In addition, both cytokines can also induce the expression of Atrogin-1 and MuRF1, suggesting that BLM-induced lung fibrosis in mice may influence the proteolysis of long-distance muscle tissues through the circulation of both IL-6 and IL-33 secreted from injured lungs during lung fibrosis." (PMID 31049028, 2019). "The development of pulmonary fibrosis in mice and differentiation of lung fibroblasts to collagen-producing myofibroblasts involves STAT3 activation by TGFß or IL-6 trans-signaling." (PMID 31694340, 2019).